WASF5P (WASP family member 5, pseudogene)
Synonyms: Em:D84394.5
Gene: Processed pseudogene on chromosome 6 (31,287,510 to 31,288,964, reverse strand). Ensembl gene ENSG00000231402.
Diseases named in the same sentence as WASF5P in open-access papers:
WASF5P is named in the same sentence as 2 diseases in open-access papers, as found by Europe PMC text mining. Sharing a sentence is not in itself a finding about the gene and the disease. The quoted sentences say what the papers report.
vitiligo (1 paper, 2022). Generalized well circumscribed patches of leukoderma that are generally distributed over symmetric body locations and is due to autoimmune destruction of melanocytes. "For example, WASF5P and LINC02571 have both been reported to be significantly associated with vitiligo in the Chinese Han population by GWAS." (PMID 36510243, 2022).
WASF5P also shares sentences with these, for which no sentence is quoted: psoriasis (1 paper).